ALK (ALK receptor tyrosine kinase)
Diseases named in the same sentence as ALK in open-access papers (continued):
Sharing a sentence is not in itself a finding about the gene and the disease.
non-small cell lung carcinoma (continued). "Indications for the drug are based on clinical trials for ALK-positive non-small cell lung cancer (NSCLC)." (PMID 33738448, 2021). "The survival of most patients with advanced stage non-small cell lung cancer is prolonged by several months when they are treated with first- and next-generation inhibitors targeting ALK rearrangements, but resistance inevitably emerges." (PMID 33467720, 2021). "About 3–7% of non-small-cell lung cancer (NSCLC) belong to a molecular subgroup defined by the presence of ALK (anaplastic lymphoma kinase) rearrangements." (PMID 34876698, 2021). "ALK gene rearrangement was observed in 3%–5% of non-small cell lung cancer patients, and multiple ALK-tyrosine kinase inhibitors (TKIs) have been sequentially used." (PMID 33627640, 2021). "Alunbrig is indicated as monotherapy for the treatment of adult patients with anaplastic lymphoma kinase (ALK)-positive advanced non-small cell lung cancer (NSCLC) previously treated with crizotinib." (PMID 34790681, 2021). "Chromosomal rearrangements involving ROS proto-oncogene 1 (ROS1) and the anaplastic lymphoma kinase (ALK) gene have been associated with many types of malignancies, including non-small cell lung cancer (NSCLC)." (PMID 34834176, 2021). "In ALK-mutated non small cell lung cancer (NSCLC), the introduction of targeted therapy with tyrosin kinase inhibitors (TKI) directed against ALK was a breakthrough in the treatment of these patients." (PMID 33799327, 2021). "Small-molecule tyrosine kinase inhibitors targeting oncogenic driver mutations (such as EGFR, ALK, ROS1 and BRAF) have fundamentally changed the treatment paradigm for non-small cell lung cancer (NSCLC)." (PMID 34037224, 2021). "In this manuscript, we provide a clinical and preclinical overview of combining radiation therapy with ALK inhibitors in anaplastic lymphoma kinase-positive non-small cell lung cancer." (PMID 34063424, 2021). "While ALK rearranged non-small cell lung cancer is exquisitely sensitive to ALK directed targeted therapies, it is generally resistant to immune-based therapies." (PMID 33806977, 2021). "In this review, we discuss the molecular epidemiology of the main druggable genetic alterations in non-small cell lung cancer, namely EGFR, KRAS, BRAF, MET, and HER2 mutations or amplification, as well as ALK and ROS1 fusions." (PMID 33435440, 2021). "Anaplastic lymphoma kinase (ALK) rearrangement status examination has been widely used in clinic for non-small cell lung cancer (NSCLC) patients in order to find patients that can be treated with targeted ALK inhibitors." (PMID 33738250, 2021). "In a large cohort of 6576 non-small cell lung cancer patients, 343 (5.2%) cases harboring ALK rearrangements were identified." (PMID 34271921, 2021). "Non-small-cell lung carcinomas with ALK or ROS1 fusions are sensitive to treatment with crizotinib and other, second- and third-generation inhibitors." (PMID 33441414, 2021). "Anaplastic lymphoma kinase (ALK) rearrangement occurs in 5% to 8% of patients with non-small cell lung cancer (NSCLC)." (PMID 34490099, 2021). "We investigated the characteristics of complex ALK rearrangements in non-small cell lung cancers using multiple molecular tests." (PMID 34271921, 2021). "Patients with non-small cell lung cancer (NSCLC) often harbor driver mutations in multiple oncogenes, including EGFR, RAS, ALK, ROS1, BRAF, HER2, RET, etc.." (PMID 34975346, 2021). "We describe a case of an anaplastic lymphoma kinase (ALK)-rearranged non-small cell lung cancer with development of uterine metastasis after crizotinib and alectinib treatment." (PMID 34184417, 2021). "ALK inhibitors effectively target EML4-ALK positive non-small cell lung cancer, but their effects are hampered by treatment resistance." (PMID 33907223, 2021).
non-small cell lung carcinoma (continued). "Studies about the efficacy of alectinib versus crizotinib in the treatment of ALK-positive non-small cell lung cancer were searched in PubMed, Scopus, Embase and the Cocharane Library from inception to February 15, 2020." (PMID 34150615, 2021). "For ALK-positive non small-cell lung cancer, targeted NGS applications were successfully used to identify ALK-specific translocation breakpoints in circulating tumor DNA (ctDNA)." (PMID 33921029, 2021). "The phase 2 ALTA trial evaluated the efficacy of brigatinib in patients with advanced ALK-positive non-small cell lung carcinoma previously treated with crizotinib." (PMID 33435596, 2021). "The prognoses of patients with non-small-cell lung cancer (NSCLC) harboring anaplastic lymphoma kinase (ALK) gene rearrangement have dramatically improved with the use of ALK tyrosine kinase inhibitors." (PMID 34943412, 2021). "ALK rearrangement represents a molecular target in a subset of non-small cell lung cancers (NSCLCs)." (PMID 33946969, 2021). "The use of tyrosine kinase inhibitors has significantly improved the outcome of patients with ALK (anaplastic lymphoma kinase)-rearranged non-small cell lung cancer." (PMID 34063424, 2021). "Lorlatinib is indicated for the treatment of patients with ALK-positive metastatic non-small cell lung cancer whose disease progressed on crizotinib and at least one other ALK inhibitor." (PMID 33435596, 2021). "We aim to describe the mechanisms by which ALK-rearranged non-small cell lung cancers escape host immunity and are thereby unresponsive to immunotherapies." (PMID 33806977, 2021). "Here, we aim to describe the mechanisms of ALK aberrations in non-small cell lung cancer by which an immunosuppressed tumor microenvironment is created, leading to host immune evasion." (PMID 33806977, 2021). "Anaplastic lymphoma kinase-rearranged (ALK+) non-small-cell lung cancer (NSCLC) is a model disease for the implementation of targeted therapies in thoracic oncology." (PMID 33959513, 2021). "Alectinib in terms of overall response rate, progression-free survival and partial response is superior to crizotinib in the treatment of ALK-positive non-small cell lung cancer and is well tolerated." (PMID 34150615, 2021). "ALK-rearrangement is observed in < 5% non-small cell lung cancer (NSCLC) cases and prior to the advent of oral tyrosine kinase inhibitors, the natural history of oncogenic NSCLC was typically poor." (PMID 32762670, 2020). "Network meta-analysis of hazard ratios for overall survival for individual ALK inhibitors among all patients (experienced and naïve) with ALK-positive non-small cell lung cancer." (PMID 32074131, 2020). "For example, BRAF and ALK inhibitors are examples that have demonstrated increased OS in melanoma and non-small cell lung cancer (NSCLC), respectively." (PMID 32188081, 2020). "Network meta-analysis of hazard ratios for progression-free survival for individual ALK inhibitors among all patients (experienced and naïve) with ALK-positive non-small cell lung cancer." (PMID 32074131, 2020). "ALK: We examined the ALK gene as it is a common biomarker in patients with non-small-cell lung cancer (NSCLC) and is the primary target of many chemotherapeutic treatments used to treat NSCLC and anaplastic large cell lymphomas (ALCL)." (PMID 33062421, 2020). "For example, non-small cell lung cancer (NSCLC) regimens are organized by EGFR, ALK, BRAF, and ROS1 mutation status; kinase inhibitors are categorized by their target kinase(s) and biomarker-specific FDA labeling is noted." (PMID 32117976, 2020). "Anaplastic lymphoma kinase (ALK) rearrangement is a common driver gene of non-small cell lung cancer (NSCLC)." (PMID 32838488, 2020). "Genomic rearrangement in anaplastic lymphoma kinase (ALK) gene occurs in 3−7% of patients with non-small-cell lung cancer (NSCLC)." (PMID 37362555, 2020).
non-small cell lung carcinoma (continued). "The US Food and Drug Administration has approved many ALK inhibitors, such as crizotinib, ceritinib, and alectinib, for the treatment of patients with non-small-cell lung carcinoma (NSCLC)." (PMID 32344689, 2020). "Crizotinib is a first generation ALK and c-Met kinase dual inhibitor, approved in 2011 for the treatment of non-small cells lung cancer (NSCLC)." (PMID 32645858, 2020). "Non-small cell lung cancer driven by genomic rearrangements of the anaplastic lymphoma kinase (ALK) gene can be successfully treated with ALK-targeted therapy." (PMID 32290439, 2020). "EML4-ALK fusions are targetable oncogenic drivers in a subset of advanced non-small cell lung cancer (NSCLC) patients that can benefit from selected ALK inhibitors." (PMID 32850382, 2020). "CGP was done in addition to established first tier reflex molecular testing as per national guidelines (e.g., EGFR/ALK for non-small cell lung cancer (NSCLC) and extended-RAS for colorectal cancer)." (PMID 32375398, 2020). "Ceritinib is an oral anaplastic lymphoma kinase (ALK) inhibitor approved for the treatment of ALK+ non-small cell lung cancer (NSCLC) in the United States1 and the European Union2." (PMID 33033286, 2020). "Targeted therapies are a standard of care for first-line treatment of Anaplastic lymphoma kinase (ALK)-rearranged non small cell lung cancer (NSCLC)." (PMID 31906956, 2020). "This study aimed to evaluate the efficacy of anaplastic lymphoma kinase (ALK)-inhibitors in the treatment of ALK-positive non-small cell lung cancer (NSCLC) by using a meta-analysis of clinical trials." (PMID 32106398, 2020). "The aim of the study is to evaluate the cost-effectiveness of alectinib for first-line treatment of ALK+ advanced non-small-cell lung cancer compared to crizotinib in the French setting." (PMID 31945065, 2020). "The clinical efficacy of ICIs for non-small-cell lung cancer (NSCLC) patients harboring major mutations, such as EGFR or ALK mutations, is limited." (PMID 32283823, 2020). "In this context, the French health authorities have requested a cost-effectiveness evaluation of the treatment of first-line ALK+ advanced non-small-cell lung cancer with alectinib compared to crizotinib in the French setting." (PMID 31945065, 2020). "For instance, EGFR T790M and C797S and ALK L1196M mutations are associated with resistance to EGFR tyrosine kinase inhibitor and ALK inhibitors in non-small cell lung cancer, respectively." (PMID 32099048, 2020). "The ALK inhibitors, crizotinib, alectinib, and ceritinib only have an indication for ALK-positive non-small cell lung cancer (NSCLC)." (PMID 33051474, 2020). "The main goal of this study was to comprehensively analyze ALK amplification (ALK-A) and ALK gene copy number gain (ALK-CNG) in a large cohort of non-small-cell lung cancer (NSCLC) patients in order to evaluate the effects on mRNA and protein expression." (PMID 32664698, 2020). "Anaplastic lymphoma kinase (ALK) rearrangements have been reported in 5% to 6% of non-small cell lung cancer (NSCLC) patients." (PMID 32212216, 2020). "Crizotinib, commercialized as Xalkori®, is an oral receptor tyrosine kinase inhibitor (TKI) targeting MET, RON, and ALK that was approved by the FDA for the treatment of non-small cell lung cancer in 2011." (PMID 31979110, 2020). "There are at present multiple small molecule agents/drugs that have been developed to inhibit c-MET, including crizotinib (XALKORI®) that is FDA approved for the treatment of ALK or ROS1 mutant expressing non-small cell lung cancer." (PMID 32983965, 2020). "About 3–5% of non small cell lung cancer (NSCLC) harbor Anaplastic lymphoma kinase (ALK)-rearrangement, mainly with echinoderm microtubule-associated protein-like 4 (EML4) as a gene partner." (PMID 31906956, 2020).
non-small cell lung carcinoma (continued). "Examples include EGFR and ALK inhibitors in non-small cell lung cancer, BRAF inhibitors in melanoma, HER2-targeting agents in breast cancer, and immune checkpoint inhibitors of CTLA4 or PDL1 in melanoma or non-small cell lung cancer 6-10." (PMID 31903155, 2020). "For example, EGFR/KRAS/ALK in non-small cell lung carcinoma, or BRAF, NRAS in melanoma, in agreement with the ESMO guidelines." (PMID 31787752, 2020). "In patients with metastatic non-small-cell lung cancer, for example, testing for EGFR mutations and ALK rearrangements, among other alterations, is critical for selecting the appropriate systemic therapy." (PMID 32637176, 2020). "We also assayed for ALK and ROS1 mutations in 211 patients with non-small cell lung cancer through ARMS-PCR." (PMID 32429938, 2020). "Mutations in the Erb-1 gene encoding EGFR are present in 10–20% of patients developing squamous cell lung cancer and rearrangements of the ALK gene are present in around 3.2% of patients developing non-small cell lung cancer (NSCLC)." (PMID 31945065, 2020). "The ALK fusion genes has been detected in approximately 2–5% of non-small cell lung cancer (NSCLC), most of which are adenocarcinoma." (PMID 33352665, 2020). "ALK rearrangement (ALK-R) has been also reported in 3–7% of all non-small-cell lung cancers (NSCLCs)." (PMID 32664698, 2020). "Anaplastic lymphoma kinase (ALK) rearrangement is a predictive factor of response to ALK inhibitors in non small cell lung cancer (NSCLC)." (PMID 32460789, 2020). "Anaplastic lymphoma kinase (ALK) gene fusions are found in 3–7% of non-small cell lung cancer (NSCLC) patients." (PMID 31513617, 2019). "The most recent receptor tyrosine kinase to be approved is lorlatinib, the first third-generation anaplastic lymphoma kinase (ALK) inhibitor approved for the treatment of patients with ALK-positive metastatic non-small cell lung cancer." (PMID 35582714, 2019). "J-ALEX trial is the first trial comparing alectinib and crizotinib as the first-line setting in advanced non-small cell lung cancer with ALK rearrangement, but only involving the Japanese population." (PMID 31023335, 2019). "The relative potency of crizotinib and selumetinib was initially examined in ALK-positive (H3122) and ALK-negative (A549) non-small cell lung cancer cells." (PMID 31827192, 2019). "Alectinib is a highly selective inhibitor of anaplastic lymphoma kinase (ALK) which has shown both systemic and central nerve system efficacy in ALK-positive non-small cell lung cancer." (PMID 31023335, 2019). "Performance was validated using 20 cfDNA samples from ALK-positive non-small cell lung cancer patients and samples from 10 healthy volunteers." (PMID 31513617, 2019). "Resistance to anaplastic lymphoma kinase (ALK)-targeted therapy in ALK-positive non-small cell lung cancer has been reported, with the majority of acquired resistance mechanisms relying on bypass signaling." (PMID 31780656, 2019). "The current standard first-line treatment for advanced non-small cell lung cancer harboring ALK rearrangement is crizotinib." (PMID 31023335, 2019). "Multiple nonhistone proteins are methylated by SMYD2 to achieve these effects on tumors, for example, MAPKAPK3 in PDAC and ALK in non-small-cell lung cancer (NSCLC)." (PMID 31370883, 2019). "The paradigm set by TKI (Tyrosine kinase inhibitors) therapy of CML (Chronic myelo id leukemia) and ALK inhibition (Anaplastic lymphoma kinase) in a small subset of patients with non-small cell lung cancer is quite compelling." (PMID 31035962, 2019). "On the other hand, anaplastic lymphoma kinase (ALK) rearrangements occur in 3-5% of patients with non-small-cell lung cancer (NSCLC), and ALK-positive patients can benefit from ALK inhibitors." (PMID 31093306, 2019).
non-small cell lung carcinoma (continued). "The identification of disease driver genes in some solid tumors holds promise for precision medicine, such as ALK inhibitors in non-small cell lung cancer with an ALK rearrangement or BRAF inhibitors in melanoma with a BRAF mutation." (PMID 31395065, 2019). "Numerous ALK fusion proteins have been described in a wide range of cancers including non-small-cell-lung-cancer (NSCLC), inflammatory immunofibroblastic tumors (IMT), and diffuse B cell lymphoma (DBCL)." (PMID 31334113, 2019). "Anaplastic lymphoma kinase (ALK) gene rearrangements are oncogenic drivers in non-small-cell lung cancer (NSCLC)." (PMID 31217479, 2019). "ALK amplification has been detected in neuroblastoma, colorectal cancer and non-small cell lung cancer (NSCLC)." (PMID 30726988, 2019). "This medication is also active against the ALK and hepatocyte growth factor receptor as proto-oncogene c-Met, especially in patients with the ALK-rearranged non-small cell lung cancer after oral administration." (PMID 32117858, 2019). "Abrogating ALK activity with kinase inhibitors is employed as clinical therapy in malignancies such as non-small cell lung cancer and has shown good results in pediatric inflammatory myofibroblastic tumors and anaplastic large cell lymphomas." (PMID 31852910, 2019). "The ALK inhibitor repotrectinib has been investigated in pre-clinical models of non-small cell lung cancer, and the results suggest an antitumor effect against cells with increased ALK activity." (PMID 31852910, 2019). "Crizotinib, has anaplastic lymphoma kinase (ALK) activity and was approved for a subset of non-small cell lung cancer found to have ALK rearrangement-driven oncogenesis." (PMID 30875928, 2019). "Constitutive activation of anaplastic lymphoma kinase (ALK) stemming from ALK rearrangement is a driving event in a portion of non-small-cell lung cancers (NSCLCs) and several other cancers." (PMID 31217479, 2019). "Anaplastic lymphoma kinase (ALK)-positive non-small-cell lung cancers (NSCLC) have the best prognosis among metastatic pulmonary malignancies, with a median patient survival currently exceeding 5 years." (PMID 31139322, 2019). "LDK378, a novel ALK inhibitor approved for advanced-stage non-small cell lung cancer (NSCLC) with ALK gene rearrangement, was recently found to have the effect of blocks 3′3’-cGAMP-induced IFNβrelease in immortalized bone marrow-derived macrophages (iBMDMs)." (PMID 30820191, 2019). "Anaplastic lymphoma kinase (ALK) gene fusions are driver genetic alterations in approximately 5% of non-small-cell lung cancers (NSCLC)." (PMID 30669647, 2019). "Single drug treatment with the small molecule ALK/MET inhibitor crizotinib has shown very promising results in adult non-small cell lung cancer and in large cell anaplastic lymphoma that harbour ALK translocations." (PMID 30778092, 2019). "Ceritinib gained US Food and Drug Administration approval in 2014 for the treatment of patients with ALK-positive metastatic non-small-cell lung cancer (NSCLC) who have progressed on or are intolerant to crizotinib." (PMID 31480400, 2019). "The development of specific therapies targeting driver alterations (e.g., EGFR mutations or ALK and ROS1 rearrangements) has changed the treatment paradigm and natural history of non-small cell lung cancer (NSCLC) harboring these aberrations." (PMID 30669267, 2019). "For instance, crizotinib, the prototype of first-generation ALK inhibitors, was primarily used to treat non-small cell lung cancer patients with ALK expression in their tumors." (PMID 31340850, 2019). "Anaplastic lymphoma kinase (ALK) is a recently identified kinase with the potential to contribute to aggressive disease in non-small-cell lung cancers." (PMID 31533238, 2019). "CZT has demonstrated high response rates in non-small cell lung cancer (NSCLC) patients carrying anaplastic lymphoma kinase (ALK (fusion gene." (PMID 30742664, 2019).